SOD1 (superoxide dismutase 1)
Diseases named in the same sentence as SOD1 in open-access papers (continued):
Sharing a sentence is not in itself a finding about the gene and the disease.
neurodegenerative disease (continued). "The deficiency SOD1 accelerated Aβ oligomerization and memory impairment in Tg2576 mouse model of AD, suggesting that SOD1 may work as a protector in neurodegenerative diseases." (PMID 29535623, 2018). "Therefore, coordinated activation of the chaperone system and protein degradation systems that include the ubiquitin-proteasome system and the autophagy system is critical to cope with the proteotoxicity of mutant SOD1 or other causative proteins of neurodegenerative diseases." (PMID 25167838, 2014). "The transition of this proof-of-concept study into a viable treatment strategy for SOD1-ALS patients and its application to other neurodegenerative disease-associated misfolded proteins warrants further research." (PMID 41213972, 2025). "For example, antisense oligonucleotides (ASOs) are used to target and degrade aberrant mRNAs associated with various neurodegenerative diseases, such as ALS (targeting SOD1 and C9ORF72)." (PMID 41255704, 2025). "Mutations in the SOD1 gene are associated with the development of ALS, a progressive neurodegenerative disease that primarily impacts both upper and lower motor neurons." (PMID 40867576, 2025). "Human SOD2 mutations are suggested to link to neurodegenerative diseases and conditions, although these associations are less clear than the ALS-links of SOD1." (PMID 40904733, 2025). "Prior work demonstrated a neuroprotective role for GPNMB in SOD1-G93A mice as well as other neurodegenerative disease models." (PMID 40700130, 2025). "ALS is a progressive neurodegenerative disease characterized by the accumulation of toxic protein aggregates, including mutant SOD1, which leads to the degeneration of motor neurons." (PMID 40978462, 2025). "This included two known proteins associated with MERCS, MFN2 and TOMM40, as well as neurodegenerative disease-associated genes such as WIPI2, CLASRP, BAG6, SOD1 and FUS which increase MERCS and MTCH2 and PARL which decrease MERCS." (PMID 38467609, 2024). "While this review is primarily focused on four specific proteins, these trends can be observed in other IDPs associated with neurodegenerative diseases such as TIA-1, hnRNP, FUS, ataxin, and SOD1." (PMID 36834792, 2023). "Canine degenerative myelopathy (DM) is an adult-onset, progressive neurodegenerative disease that shares important similarities to ALS including clinical presentation and progression, pathological features, and SOD1 mutations." (PMID 36495266, 2023). "The SOD1, SOD2, and FIS1 genes of yeast cells are homologous to those in humans, and mutation or change of expression of these genes in humans is related to neurodegenerative diseases." (PMID 36829855, 2023). "C9orf72-specific up-regulated protein change revealed the involvement of the TOR pathway (online resource), meanwhile FUS and SOD1 shared common features in terms of RNA processing and neurodegenerative diseases-related pathways (online resource)." (PMID 37488208, 2023). "This phenomenon observed in our study is consistent with prior studies in other neurodegenerative diseases, and a recent report on soluble misfolded SOD1 being the disease driver in ALS disease." (PMID 38015828, 2023). "Together, these results reveal a role for α2-Na+/K+-ATPase in SOD1 aggregation and highlight the critical effect of temporal modulation of genetically validated therapeutic targets in neurodegenerative diseases." (PMID 38015828, 2023). "Other than the main effects of sleep deprivation on immune‐system function, plasma proteins associated with neurodegenerative diseases (APP, NOTCH3, SNCA, SOD1) were decreased after sleep deprivation, while only ATF6 continued to increase." (PMID 37139463, 2023). "This is the first study that demonstrates a D-DT mechanism of action in neurodegenerative diseases, specifically in SOD1-related fALS." (PMID 35688953, 2022).
neurodegenerative disease (continued). "To investigate changes in CNS resident immune cells, we sorted spinal cord microglia and found that antibiotics downregulated homeostatic genes and increased neurodegenerative disease genes in SOD1 mice." (PMID 35272713, 2022). "In contrast to many other proteins involved in late-onset neurodegenerative diseases, mature SOD1 is highly stable, forming a homodimer containing Cu and Zn cations." (PMID 34943155, 2021). "This makes the REST2 approach useful for identifying misfolded states of SOD1 and other proteins involved in neurodegenerative diseases." (PMID 34943155, 2021). "In many familial neurodegenerative disease cases, mutant proteins such as Aβ in AD, parkin, DJ-1, and α-synuclein in PD, huntingtin in HD, and superoxide dismutase 1 (SOD1) in ALS can localize to the mitochondria." (PMID 34776869, 2021). "Summary of clinical trials with reported effects on SOD1 function and/or misfolding in neurodegenerative diseases." (PMID 32144830, 2021). "Such advances highlight the potential of treatment strategies aimed at altering or rectifying atypical SOD1 biochemistry, in particular SOD1 metalation, as disease‐modifying therapies for neurodegenerative diseases." (PMID 32144830, 2021). "Repurposing chemotherapeutic agent of cisplatin for curing neurodegenerative disease also raises SOD1 dimer stability and inhibits oligomerisation of metal-free SOD1." (PMID 32862101, 2020). "Among many of the aggregation-prone proteins that are responsible for different neurodegenerative diseases, anomalous aggregation of mutant SOD1 protein leads to ALS." (PMID 35492906, 2020). "By taking advantage of the prion-like nature of Aβ, tau, α-syn, TDP-43, SOD1, and mHtt, organotypic slice culture models of the corresponding neurodegenerative diseases have been significantly enhanced." (PMID 32698402, 2020). "Mutations in superoxide dismutase (SOD1) are the second most common cause of familial ALS, a progressive neurodegenerative disease characterized by the loss of motor neurons in the brain and spinal cord." (PMID 33114780, 2020). "Induced-fit complexation is reliant on the structural plasticity of the immature SOD1 disulphide sub-loop, a characteristic which contributes to misfolding and aggregation in neurodegenerative disease." (PMID 30735496, 2019). "Canine DM is an inherited, progressive, adult-onset neurodegenerative disease with clinical, histopathologic, and genetic parallels to human ALS, including presence of mutated superoxide dismutase 1 gene (SOD1)." (PMID 30674036, 2019). "For example, neurodegenerative disease-related protein aggregates, such as polyglutamine, huntingtin, ataxin-1, and superoxide dismutase-1, block clathrin-mediated endocytosis and intracellular trafficking in neurodegenerative disease." (PMID 30866990, 2019). "Abnormal changes of wild-type SOD1 have been reported also in the other neurodegenerative diseases such as Alzheimer’s disease (AD) and Parkinson’s disease (PD)." (PMID 31744522, 2019). "Mitochondrial dysfunction has been broadly implicated in the pathogenesis of neurodegenerative diseases including ALS, and impaired mitochondrial function is observed in human fALS SOD1 mutant cultured fibroblasts." (PMID 31213966, 2019). "Several neurodegenerative disease proteins including Aβ, tau, α-syn, mutant huntingtin, mutant SOD1, and TDP-43 misfold and self-propagate through templated recruitment." (PMID 30310141, 2018). "With regards to the other cytoskeletal abnormalities observed, a decrease in neurofilament has also been reported in NSC-34 cells expressing mutant SOD1, as an in vitro model of the neurodegenerative disease, ALS." (PMID 29462312, 2018). "Degeneration of neuronal processes has been previously reported in a single-copy ALS SOD1 mouse model and in other C. elegans models of neurodegenerative disease." (PMID 30296255, 2018).
neurodegenerative disease (continued). "This study has significantly confirmed the potential of CRISPR/Cas9 as a successful tool for the treatment of SOD1-linked forms of ALS and other neurodegenerative diseases." (PMID 29562705, 2018). "The ability to buffer calcium is a fundamental property of brain mitochondria, which is altered in various mouse models of neurodegenerative diseases, including familial ALS associated with mutant SOD1." (PMID 28482850, 2017). "Abnormal expression of Nrf2, GCLc, SOD1, and SOD2 has been reported to be associated with PD and other neurodegenerative diseases." (PMID 29234413, 2017). "These genes were grouped according to specificity and association strength 1) to the individual mouse models, 2) to both aging models (physiological aging + Ercc1 accelerated aging), or 3) to both neurodegenerative disease models (App-Ps1 + Sod1)." (PMID 26001565, 2015). "In contrast, the mutant SOD1 possesses a toxic property that is responsible for the pathogenic mechanism of ALS, a neurodegenerative disease associated with the degeneration of motor neurons, muscle atrophy, and paralysis." (PMID 26491230, 2015). "The respective membrane behavior was analyzed by investigating specific types of Cu/Zn-superoxide dismutase (SOD1) species, which are linked to neurodegenerative disease." (PMID 25587400, 2013). "In conjunction with this, it is notable that there are several neurodegenerative diseases for which research into ASO therapy is already being performed, including the form of ALS caused by mutations in the SOD1 gene (NCT01041222)." (PMID 24349764, 2013). "Common in neurodegenerative diseases are cytoplasmic protein aggregates, including mutant or the wild type proteins of SOD1, TDP-43, and FUS/TLS." (PMID 23281774, 2013). "As a response to accumulation of misfolded ER proteins, the expression of gp78 is increased by accumulation of neurodegenerative disease proteins, such as mutant htt, SOD1, and ataxin-3." (PMID 20126661, 2010). "We hypothesized that pathological SOD1 might propagate more than WT-SOD1, leading to progressive neurodegenerative disease." (PMID 40350531, 2025). "Interestingly, proteins known to be implicated in neurodegenerative diseases other than AD, such as SNCA, pSNCA-129, Oligo-SNCA, SOD1, and TARDBP were also significantly associated with AD." (PMID 40678230, 2025). "The situation in a primary neurodegenerative disease may be quite different, and the consensus is that glial (inflammatory) responses drive disease progression in the SOD1-G93A ALS mice." (PMID 38928564, 2024). "Finally, future work against SOD1-associated ALS, and even other neurodegenerative diseases, should incorporate our growing knowledge of the root mechanisms and downstream effects into therapy design." (PMID 35065969, 2022). "In contrast, patients with a family history for other neurodegenerative diseases were more likely to carry a mutation in other ALS/FTD genes (20% vs. 4.1% in fALS-ALS corresponding to only one patient, #ALS82, also carrying a SOD1 mutation) as an inheritable trait." (PMID 33770234, 2021). "In addition, proteins including SOD1, α-synuclein, and apoE, which all bind VDAC1 have been implicated in affecting intraneuronal Ca2+ in several neurodegenerative diseases." (PMID 33114780, 2020). "According to cellular component analysis, the validation of SOD1 may facilitate the understanding of the relationships between common neurodegenerative diseases such as IS." (PMID 32174813, 2020). "Cerebrospinal fluid (CSF) from patients including sALS as well as several other neurodegenerative diseases and non-neurodegenerative diseases was examined with an immunoprecipitation assay and a sandwich ELISA using antibodies specifically recognizing misfolded SOD1." (PMID 31744522, 2019). "Additionally, alsin has been shown to antagonize the effects of SOD1 mutants on motor neuronal death in a Rac1-dependent manner, further highlighting the protective role of Rac1 in neurodegenerative diseases." (PMID 27442895, 2017).
neurodegenerative disease (continued). "This study provides evidence for a novel interaction of α-synuclein and SOD1 that might be relevant for neurodegenerative diseases." (PMID 26643113, 2015). "Besides SOD1, cytosolic misfolded proteins involved in neurodegenerative diseases, such as α-synuclein and Tau, have been found in exosomes, and a high level of exosome-associated phosphorylated Tau was found in CSF of Alzheimer patients." (PMID 23592792, 2013). "Some of the familial forms of neurodegenerative diseases present mutations in genes that have association with mitochondrial function such as PTEN-induced putative kinase (PINK1), Parkin, DJ-1, alpha-synuclein, mitofusin (MFN) 2, and Cu/Zn superoxide dismutase (SOD1) among others." (PMID 35990893, 2022). "Upregulated miR-155 has been examined in both pre-symptomatic and symptomatic stages of disease in SOD1 mice models, and is known to regulate microglial responses and NF-kB-controlled responses in neuroinflammation as well as other immune responses in diverse neurodegenerative diseases." (PMID 32422969, 2020). "Therefore, restoring Tbk1 function might provide therapeutic benefits for both Tbk1- and SOD1-related neurodegenerative diseases." (PMID 31039129, 2019). "As in the other neurodegenerative diseases, it appears unlikely that the visible SOD1-containing inclusions themselves are toxic; rather their presence suggests that smaller, soluble high molecular weight oligomeric precursor species containing SOD1 are being generated in vivo." (PMID 18301754, 2008). "Because electromyography (EMG) can detect neurogenic damage before pathological features of neurodegenerative disease emerge, EMG was used to monitor early stages of disease in SOD1 G93A mice (relative to control mice) (Fig. EV7A)." (PMID 41094045, 2025). "By integrating crystallographic data with computational modeling, we bridge the gap between basic structural biology and therapeutic discovery, offering a foundation for future studies aimed at targeting SOD1 in ALS and other neurodegenerative diseases." (PMID 40362464, 2025). "Like in other neurodegenerative diseases such as Alzheimer’s disease, ALS is characterized by an abnormal accumulation of proteins, some of which are mutant SOD1 proteins." (PMID 38483584, 2024). "For example, by modulating linear ubiquitination, LUBAC induces proteasomal degradation of aberrantly aggregated proteins, including mutant Huntingtin, Ataxin-3, SOD1, and TDP-43, which all are involved in neurodegenerative disease." (PMID 34737388, 2022). "However, what appears to differentiate the pathological outcomes, of the neurodegenerative diseases, are the presence of disease-specific “endogenous factors,”' which trigger the inflammatory processes: amyloid-beta for AD, α-synuclein for PD, mutant SOD1 for ALS, and myelin-peptide-mimetic for MS." (PMID 34408721, 2021). "In contrast to SOD1-ALS, protein aggregates found in other neurodegenerative diseases, including amyloid-β plaques in AD and Lewy bodies in PD, have been shown to have a high metal content (iron, copper or zinc)." (PMID 24982630, 2014). "In this study, we have investigated the effects of components of the CSF metabolome over SOD1, a protein that undergoes toxic aggregation in ALS, a fatal neurodegenerative disease." (PMID 24048249, 2013). "In contrast, D3-1 did not recognize SOD1 in patients with sporadic ALS or other neurodegenerative diseases." (PMID 36874245, 2023). "Despite this, our findings of misfolded SOD1 in CSF raise lots of fresh questions that should be tested in the future; for example, roles of those misfolded SOD1 species in a pathomechanism of ALS and other neurodegenerative diseases remain totally unknown." (PMID 31744522, 2019). "The SOD1 misfolding in CSF of sALS and the other neurodegenerative diseases has not been well characterized and is just emerging; therefore, more data need to be accumulated for development of the CSF-based cures of ALS." (PMID 31744522, 2019).
neurodegenerative disease (continued). "In particular, our hypothesis is that histamine should be able to counteract the pro-inflammatory phenotype of SOD1-G93A microglia, if indeed histamine exerts in ALS an anti-inflammatory role as previously demonstrated in other neurodegenerative diseases." (PMID 29250069, 2017). "In conclusion, our data demonstrate that the aberrant accumulation of SOD1 aggregates in cells impairs the turnover of SOD1 protein, and highlight the importance of the protein degradation pathways, namely the UPS, in the progression of neurodegenerative diseases such as ALS." (PMID 34803609, 2021). "If newly synthesised SOD1 is not correctly processed by the addition of copper, zinc, and an unusual disulphide bond, it will remain inactive or can misfold, as is the case in some neurodegenerative diseases." (PMID 30735496, 2019). "Although the increased expression of Cox-2 in ALS patients and SOD1 mutant mice has been reported, one more interesting discovery is that the expression of Cox-2 is specifically increased in ALS patients rather than other neurodegenerative disease cases." (PMID 30976389, 2019). "Therefore, the finding of a potential suppression of SNAP25, with or without ATF3 getting involved, in SOD1-mutant ALS patients might indeed be of importance and point to a general role in neurodegenerative diseases." (PMID 37491426, 2023). "Exosomes participate in the propagation of misfolded SOD1 and TDP-43 proteins, in aberrant phenotype of immune cells and could impair synaptic plasticity in neurodegenerative diseases." (PMID 29354030, 2017).
cardiovascular disease (50 papers, 2012 to 2025). "Considering the role of SOD1, it is possible that variation in the gene encoding this protein is related to cardiovascular disease hereditability." (PMID 27755600, 2016). "Previous reports demonstrated that some SOD1 SNPs are associated with the development of cardiovascular disease." (PMID 27755600, 2016). "The results could have introduced the 50 bp INS/DEL polymorphism of SOD1 genotyping as a new and distinct diagnostic method for identifying high-risk cardiovascular diseases." (PMID 40867576, 2025). "The presence of an additional copy of genes on chromosome 21 (i.e., the superoxide dismutase 1 gene (SOD1) and gene coding for the cystathionine β-synthase (CBS) enzyme) raises the risk for cardiovascular disease (CVD)." (PMID 36551975, 2022). "Although family history examined by self-reported questionnaires often includes recall bias, these results raised the possibility that DNA variation of SOD1 contribute to cardiovascular disease heritability." (PMID 27755600, 2016). "The results of this study revealed that the rs1041740 TT carriers in the SOD1 gene had a higher level of BNP and a more frequent family history of cardiovascular disease compared to TC and CC carriers." (PMID 27755600, 2016).